GAP43 (growth associated protein 43)
Diseases named in the same sentence as GAP43 in open-access papers (continued):
Sharing a sentence is not in itself a finding about the gene and the disease.
tauopathies (2 papers, 2022 to 2024). "Gap43 is well known as a primary JNK-targeted axonal phospho-protein with elevations in AD CSF associated with tauopathy that predict progression." (PMID 38542311, 2024). "Another limitation of this study is its lack of evaluation of other tauopathies such as FTD, PSP, and CBS, which limits analysis of association between CSF GAP-43 and tau pathology in other tauopathies." (PMID 36253408, 2022).
ZIKV infection (2 papers, 2018 to 2020). "Proteins previously identified to be differentially expressed during ZIKV infection include GAP43, DCX, PTPRZ1, ASNS, SLC3A2 and MKI67." (PMID 32873194, 2020). "Many of these proteins have been shown to be related to cellular functions of neural cells, and are found to play roles in cell signaling processes, such as DCX, EGFR, and GAP43, indicating the alteration of multiple cell signaling pathways in NPC by ZIKV infection." (PMID 29922247, 2018).
acute appendicitis (1 paper, 2022). "In the appendix, Di Sebastiano examined appendectomy specimens of 15 cases of non-acute appendicitis for the alterations in peptidergic innervation for VIP and GAP-43 using immunohistochemical methods." (PMID 35741196, 2022). "The non-acute appendices were characterized by an increased expression of GAP-43 and larger amounts of SP-immunoreactive and VIP-immunoreactive nerves in the mucosal layer, as compared to appendices with acute appendicitis." (PMID 35741196, 2022).
allergic contact dermatitis (1 paper, 2015). An inflammatory skin condition caused by an immune response to direct contact between the skin and an allergen. "GAP-43–immunoreactive IENFs were also decreased in highly inflamed psoriasis skin areas, whereas a significant increase of GAP-43–positive IENFs was shown in human allergic contact dermatitis in eczematous skin compared with control skin." (PMID 26503622, 2015).
anaplastic gliomas (1 paper, 2023). "In this study, we analyzed the expression of GAP-43, Cx43 and actin as fundamental markers of TMs-mediated distant intercellular communication in samples of 118 patients, harboring diffuse or anaplastic glioma." (PMID 36739296, 2023). "We therefore aimed to investigate the expression of GAP-43, Cx43 and actin in relation these parameters as well as in relation to overall survival (OS) in diffuse and anaplastic gliomas." (PMID 36739296, 2023). "The intercellular distant communication network in diffuse and anaplastic gliomas formed by actin and GAP-43 is associated with a negative impact on overall survival and with unfavorable prognostic features." (PMID 36739296, 2023). "More than 80% of diffuse and anaplastic gliomas showed moderate or strong GAP-43 expression." (PMID 36739296, 2023).
atrial fibrillation (1 paper, 2008). A disorder characterized by an electrocardiographic finding of a supraventricular arrhythmia characterized by the replacement of consistent P waves by rapid oscillations or fibrillatory waves that vary in size, shape and timing and are accompanied by an irregular ventricular response. "An increase of GAP43 positive nerves in dogs with atrial fibrillation suggests its involvement in sympathetic hyperinnervation." (PMID 21876659, 2008).
autism spectrum disorder (1 paper, 2018). A spectrum of developmental disorders that includes autism, and Asperger syndrome. "Interestingly, Fmr1 KO mice presented less spontaneous freezing behavior compared to WT, consistent with previous studies in GAP43 mice model of autism spectrum disorder and probably reflecting some aspects of maladaptive behavior to stress and catatonia in patients." (PMID 30333723, 2018).
cardiac arrest (1 paper, 2025). Cessation of breathing and/or cardiac function. "In mouse models of cardiac arrest-induced neuronal death, tDCS enhanced expression of proteins related to synaptic function and regeneration, including MAP2, GAP43, PSD95, and synaptophysin." (PMID 41440017, 2025).
cervical cancer (1 paper, 2024). A primary or metastatic malignant neoplasm involving the cervix. "The reprogramming-related genes, including transcription factors (CJUN), myelin genes (MBP), neurotrophic factors and receptors (BDNF, NGFR) and axonal regenerative marker (GAP43) were significantly elevated upon RSC96 cells co-cultured with cervical cancer cells." (PMID 39214988, 2024).
chronic inflammatory demyelinating polyneuropathies (1 paper, 2022). "The only longitudinal study to our knowledge that showed a change in GAP-43 was a small case report on two patients with chronic inflammatory demyelinating polyneuropathies." (PMID 36383568, 2022).
cognition (1 paper, 2022). Intellectual or mental process whereby an organism becomes aware of or obtains knowledge. "Next, GEE was utilized to test the associations between baseline CSF GAP-43 level and cognition decline, after adjustment for age, sex, and education." (PMID 36611808, 2022).
deafness (1 paper, 2014). An inherited or acquired condition characterized by the complete loss of the ability to hear from one or both ears. "Remarkably, this deafness-dependent induction of bilaterally asymmetric expression of Gap43 mRNA appeared to be stable." (PMID 24647228, 2014). "However, total deafness of only one ear quickly results in an asymmetric change of gap43 transcription when comparing both sides of the brainstem." (PMID 24647228, 2014). "However, development of Gap43 protein within these neuronal somata, likely to be LOC neurons, required at least 5 days of deafness or chronic EIS." (PMID 24647228, 2014).
embryonal carcinoma (1 paper, 2019). A non-seminomatous malignant germ cell tumor characterized by the presence of large germ cells with abundant cytoplasm resembling epithelial cells, geographic necrosis, high mitotic activity, and pseudoglandular and pseudopapillary structures formation. "We have also observed that hANG associates with GAP-43 in the early stages of neuronal differentiation from embryonal carcinoma cells." (PMID 30710110, 2019).
endometriosis (1 paper, 2020). The growth of functional endometrial tissue in anatomic sites outside the uterine body. "Only the endometriosis lesions retrieved from the SP group showed lower GAP43 positivity." (PMID 32230898, 2020).
gastric cancer (1 paper, 2021). A primary or metastatic malignant neoplasm involving the stomach. "Incidentally, we also found that GAP43 is differentially expressed, elevated or decreased in gastric cancer." (PMID 33402155, 2021). "However, we found that patients with gastric cancer who were treated with the 5-FU anticancer drug had higher survival rates in patients with high GAP43 expression than those with low expression." (PMID 33402155, 2021). "Survival analysis showed that there was no significant change in survival of gastric cancer patients with low or high expression of GAP43." (PMID 33402155, 2021).
granular cell nerve sheath tumour (1 paper, 2022). "The term “granular cell nerve sheath tumour” might be more descriptive of this relatively rare lesion, and an appropriate immunophenotypic and molecular panel (including GAP43) should be implemented in the diagnosis of GCTs." (PMID 35323240, 2022).
Hallucinations (1 paper, 2020). Perceptions in a conscious and awake state that, in the absence of external stimuli, have qualities of real perception. "CSF Ng levels were associated with disinhibition, and GAP-43 levels displayed negative correlations with both hallucinations and disinhibition, while NFL was associated with hallucinations." (PMID 33203439, 2020).
heart failure (1 paper, 2024). Inability of the heart to pump blood at an adequate rate to meet tissue metabolic requirements. "First, Nox2 deficiency reduces myocardial oxidative stress, attenuates decreased catecholaminergic histofluorescence profiles, and restores protein expression levels of PGP9.5, GAP43, tyrosine hydroxylase and NET in doxorubicin-induced heart failure." (PMID 38521855, 2024).
Hyperglycemia (1 paper, 2021). An increased concentration of glucose in the blood. "Our results demonstrated that GAP-43 and KIF5B protein expression between C, DC, DT and T groups was significantly different, demonstrating that GAP-43 and KIF5B protein levels in the rat gastrocnemius skeletal muscle fibers were affected by both ET and hyperglycemia." (PMID 33953268, 2021).
leprosy (1 paper, 2022). Leprosy is a chronic infectious disease affecting primarily the skin and peripheral nervous system. "We also described a molecular signature associated with neural damage in early stages of pure neural leprosy from patients (i.e., HLA-DRB1, MAPK14, GAP43, FABP7, NTN1, and LRRTM4)." (PMID 35492305, 2022).
lumbar spinal stenosis (1 paper, 2025). A spinal stenosis that involves the lumbar region of vertebral column. "The observed increase in GAP-43 protein levels in the ligamentum flavum may reflect a compensatory neuroplastic response to ischemic nerve root injury—a key pathological mechanism in lumbar spinal stenosis." (PMID 40004753, 2025).
medulloblastoma (1 paper, 2012). A malignant, invasive embryonal neoplasm arising from the cerebellum. "Taken together, these results indicate that Nos2 deficiency promotes medulloblastoma development in Ptch1+/− mice through retention of proliferating GCPs in the external granular layer due to reduced Gap43 expression." (PMID 22438824, 2012).
metastasis (1 paper, 2018). The spread or migration of cancer cells from one part of the body (where they first appeared) to another. "In our RNA sequencing data, we found that the neurite/neuronal marker, Gap43 and β3 tubulin, were significantly up-regulated in the stroma of osteolytic bone metastasis." (PMID 29988965, 2018). "In the RNA sequencing data genes linked to arteries (Elastin, Lamb1, Acta2), pericytes (Cspg4/Ng2, Pdgfrb, Sca1 (Ly6a)) and neurons/neurites (Gap43, Tubb3) were up-regulated in the stroma of osteolytic bone metastasis." (PMID 29988965, 2018).
pancreatitis (1 paper, 2025). Inflammation of the pancreas. "GAP43 has been associated with neuronal plasticity and shown to have increased expression in nerves in PDAC and pancreatitis." (PMID 40075699, 2025).
papillary thyroid cancer (1 paper, 2019). "By analysis of the next‐generation resequencing of paired papillary thyroid cancer (PTC) and adjacent thyroid tissues, we found that Growth Associated Protein 43 (GAP43), a phosphoprotein activated by protein kinase C, might be novel markers associated with PTC." (PMID 31568662, 2019).
pheochromocytoma (1 paper, 2025). "We first tested the GAP-43 phosphomutants in PC12 cells, a rat pheochromocytoma cell line capable of differentiating into neuronal-like cells upon exposure to soluble Nerve Growth Factor or transfection with neuronal growth proteins such as GAP-43." (PMID 40259946, 2025).
posterior cortical atrophy (1 paper, 2024). Posterior Cortical Atrophy (PCA) is a rare progressive neurodegenerative disorder with a typical onset between 50-65 years of age characterized by progressive impairment of higher visual processing skills and other posterior cortical functions without any evidence of ocular abnormalities. "Elevated level of CSF GAP-43 was specific to AD compared to the other neurodegenerative diseases, e.g., MCI, ALS, behavioral variant FTD (bvFTD), PD, DLB, primary progressive aphasia (PPA), progressive supranuclear palsy, corticobasal syndrome, and posterior cortical atrophy (PCA)." (PMID 38659704, 2024).
prion disease (1 paper, 2026). A transmissible disease that is caused by a protein that is able to induce abnormal folding of normal cellular proteins, leading to characteristic spongiform brain changes, which are associated with neuronal loss without an inflammatory response. "Growth-associated protein-43 (GAP43) is a neuronal protein essential for synaptic function and plasticity, and its reduction has been observed in brains of prion diseases (PrDs) and rodent models." (PMID 41751815, 2026).
proteinopathies (1 paper, 2025). "The inclusion of GAP43 cryptic exon 4a1 may serve as a hallmark of TDP‐43 proteinopathies, highlighting a mechanistic link between TDP‐43 dysfunction and neuronal vulnerability." (PMID 40583130, 2025).
relapsing-remitting MS (1 paper, 2019). "Significantly lower CSF GAP-43 concentrations were found in progressive MS [1640 (1120–1950) pg/mL, p = 0.004], but not in relapsing-remitting MS (RRMS) [2270 (1620–2830) pg/mL, p = 0.8], compared with healthy controls (HCs) [2340 (1580–3230) pg/mL]." (PMID 31754174, 2019). "We aimed to evaluate if GAP-43 can serve as a biomarker of regeneration in relapsing-remitting MS (RRMS) and whether disease-modifying therapies (DMTs) influence GAP-43 concentration in cerebrospinal fluid (CSF)." (PMID 31754174, 2019).
retinoblastoma (1 paper, 2025). A malignant tumor that originates in the nuclear layer of the retina. "Interestingly, the level of expression of UBE2C, EBF3, GAP43, and PDC was reminiscent of a profile of non-proliferative subtype 1 retinoblastoma (cluster 1 population), also cited in previous studies as cone precursors and cone precursor-like." (PMID 40898088, 2025).
rheumatoid arthritis (1 paper, 2015). A chronic, systemic autoimmune disorder characterized by inflammation in the synovial membranes and articular surfaces. "Whether humans with rheumatoid arthritis show enhanced GAP-43 expression has not been explored, to our knowledge." (PMID 26503622, 2015).
small fiber neuropathy (1 paper, 2017). "A diagnosis of small fiber neuropathy is confirmed by quantifying nerve fibers in skin biopsies using sensory nerve markers including βIII tubulin and growth associated protein 43 (GAP43)." (PMID 28973369, 2017).
spinal stenosis (1 paper, 2025). Narrowing of the spinal canal. "One significant limitation is its cross-sectional design, which precludes establishing causality between GAP-43 expression and degenerative changes in spinal stenosis." (PMID 40004753, 2025). "Identifying the role of GAP-43 in this context could reveal new insights into the mechanisms underlying ligament hypertrophy and spinal stenosis." (PMID 40004753, 2025). "Specifically, GAP-43 may enhance synaptic remodeling and nerve sprouting in response to nerve root compression, potentially amplifying pain perception and contributing to chronic pain syndromes associated with spinal stenosis." (PMID 40004753, 2025). "Future research should explore whether interventions targeting pain modulation could more effectively reduce GAP-43 expression and improve clinical outcomes in patients with spinal stenosis." (PMID 40004753, 2025).
Ventricular arrhythmia (1 paper, 2022). "Inhibition of microRNA-155 expression in recruited macrophages in a MI mouse model displays decreased density of tyrosine hydroxylase and GAP43 (neuromodulin) positive nerve fibers in myocardial tissue, which was associated with reduced ventricular arrhythmias." (PMID 35812333, 2022).
tumor (52 papers, 2017 to 2025). "Growth-associated protein 43 (GAP43) is a significant structural protein of tumor microtubes and is important for the formation of TNTs, particularly in GBM." (PMID 39924629, 2025). "In astrocytoma, many tumor cells extend ultralong membrane protrusions and use these distinct tumor microtubes through growth-associated protein-43 as routes for enhancing brain invasion." (PMID 36105204, 2022). "Growth-Associated Protein-43 (GAP43) is essential for the development of TMs and, thus, the tumor cell network associated with GB progression." (PMID 31846454, 2019). "Genetic knock-down of GAP43 led to deficiencies in tumor-microtube formation causing a distinct reduction of tumor size in the mouse brain and to an improved survival of the animals." (PMID 31058089, 2019). "VPA increases the expression of genes involved in tumor differentiation and progression that are regulated by the ERK-AP-1 pathway, including growth-associated protein-43 (GAP-43) and Bcl-2." (PMID 40722968, 2025). "Mitochondrial transfer from astrocytes to GBM, facilitated by GAP43, promotes proliferation and tumor growth." (PMID 39924629, 2025). "Recent studies showed that TAAs also transfer mitochondria to GBM cells via growth-associated protein 43 (GAP43)-positive tumor microtube-like structures, and TGFβ, enhancing ATP production and promoting tumor growth, aggressiveness, and therapy resistance." (PMID 39859381, 2025). "Astrocytes interact with GBM cells to promote tumor growth, invasion, and therapy resistance, partly through extracellular vesicles and mitochondrial transfer mediated by GAP43." (PMID 40018519, 2025). "Confocal microscopy revealed that GAP43‐positive tumor cells displayed long and continuous membranes with protrusion tips, similar to neural growth cones." (PMID 39473365, 2025). "Computational deconvolution of two of the previous bulk studies confirmed the higher expression of GAP43 in MBM compared to ECM in the deconvoluted tumor cells." (PMID 40954493, 2025). "Comparing tumours from the control group, the minimal residual disease stage and regrown tumours identified GAP43 as strongly differentially expressed, with a low expression at the minimal residual disease stage, but increasing in the regrown tumours." (PMID 39609432, 2024). "As a further proof of concept for the accuracy of the SC-related 43-gene set to predict peripheral neuron abundance in the TME, we examined FFPE tumor sections from a HNSCC cohort (n = 50) by IHC staining with an anti-GAP43 antibody." (PMID 38920662, 2024). "This work highlighted the relevance of the interconnected network of GBM cells formed by GAP43+ MTs for tumor growth." (PMID 37169842, 2023). "Several groups identified biomarkers of TNTs, also named cytonemes or tumor microtubes, including Connexin43, GAP43, 14-3-3-γ, TTHY1, and several mitochondrial/vesicular markers." (PMID 37476291, 2023). "Tumor cells within the PD-GBO form a morphological interconnecting tumor network proficient for nestin, Gap43, Connexin 43, and the astrocytic marker GFAP." (PMID 35743016, 2022). "We observed that NNMT promoted SIRT1 and inhibited GAP43 expression, thereby promoting tumor cell proliferation and invasion." (PMID 35884600, 2022). "In contrast, an overexpression of GAP43 transformed TM-poor oligodendroglioma cells into an interconnected tumor-tumor cell network." (PMID 36357661, 2022). "GAP43 can inhibit the formation of microtubules in tumor and intertumor cell network connections and induce apoptosis through the SIRT1 signaling pathway." (PMID 35884600, 2022). "Quantification of the distribution of the staining for TNT-associated proteins, 14-3-3γ and GAP43, as well as PCNA and GFAP, indicates the exquisite distribution of all these components at the tumor-tissue interface." (PMID 34267246, 2021). "All cells from clusters 0 and 2 (CRX+/EBF3+/GAP43+ tumor cells), and some cluster 3 cells, corresponded to the first profile (multiple alterations)." (PMID 34552068, 2021).